IL17A (interleukin 17A)
Diseases named in the same sentence as IL17A in open-access papers (continued):
Sharing a sentence is not in itself a finding about the gene and the disease.
psoriasis (continued). "Our group has shown that IL-15 and IL-23 act synergistically on cocultures of CLA+ memory T cells and autologous epidermal cells to produce significantly increased levels of IL-17F and IL-17A in psoriasis when compared to CLA− T cells cocultures." (PMID 34778294, 2021). "Ixekizumab, a recombinant humanized IgG4-κ monoclonal antibody (mAb) that selectively binds and neutralizes IL-17A, has been employed clinically for psoriasis since 2015." (PMID 33602246, 2021). "In the current study, the severity of psoriasis was significantly correlated with the increase in serum IL-17A levels (r: 0.373, P = 0.013)." (PMID 33356031, 2021). "In case of IL-17A, the median RQ in skin was 119.636 in the psoriasis group and 2.217 in the control group, but below detection levels for both groups in lymphocytes." (PMID 34945130, 2021). "Both IL-22 and IL-17A promoted induction of AMP; they are implicated together in the inflammatory processes involved in cases of psoriasis, inflammatory bowel diseases, and rheumatoid arthritis." (PMID 34805416, 2021). "To validate the expression of the key enzymes of NAD metabolic pathways in psoriasis lesions, we collected skin samples from patients affected by plaque psoriasis and undergone to therapeutic treatment with the anti-IL-17A antibody, secukinumab." (PMID 34202251, 2021). "Previous studies have evaluated the levels of miR-1266, miR-340 and miR-197, which are thought to act via IL-17A in patients with psoriasis." (PMID 33356031, 2021). "Keratinocytes appear to be the main source of IL-25 in psoriasis, and its expression is tightly regulated by IL-17A." (PMID 34201664, 2021). "Studies of murine models of psoriasis have similarly proven increases in cutaneous and serum IL-17A and IL-22 levels after TNF-α blockade." (PMID 34211394, 2021). "Particularly, glycyrrhizin improves psoriasis by inhibiting the secretion of IL-17A and IFN-γ in TH17 cells." (PMID 34044769, 2021). "To further evaluate the role of the IL-17A–IL-36γ cytokine axis for the pathomechanism of psoriasis, we established an ear injection model." (PMID 34440590, 2021). "During the pathogenesis of psoriasis, neutrophils mainly produced IL-17A, which was an important cytokine leading to psoriatic dermatitis." (PMID 34512732, 2021). "A significant increase in serum and tissue levels of IL-17A in patients with psoriasis has been reported." (PMID 33356031, 2021). "Neutrophils infiltration, besides the high value of the IL-17A in the G6 group, indicates the role of IL-17A, IL-23/Th 17 axis in the pathogenesis of psoriasis that is mediated by neutrophils” infiltration." (PMID 33253155, 2020). "Recently, γδT cells have been reported to be a major IL-17A producer in human psoriatic lesion and mouse psoriasis-like skin inflammation." (PMID 32454795, 2020). "Secondly, quantification of local and systemic levels of both IL-17 cytokines in patients with psoriasis, psoriatic arthritis, and ankylosing spondylitis revealed a greater abundance of IL-17F relative to IL-17A (>30-fold)." (PMID 32973785, 2020). "In psoriasis patients, the neutralization of IL-17A by ixekizumab or secukinumab significantly decreases histological acanthosis, the number of Ki-67+-proliferating keratinocytes, and epidermal cytokeratin 16 expression." (PMID 32070069, 2020). "Case reports of IBD in psoriasis patients receiving ixekizumab, a second IL-17A antibody, have been reported, although post hoc analyses of ixekizumab trials suggest that IBD is a rare adverse outcome." (PMID 32697969, 2020). "For example, treatment with secukinumab and ixekizumab, a monoclonal antibody that selectively neutralizes IL-17A, resulted in a reduction of psoriasis-related scalp pain and itching." (PMID 33133059, 2020). "In psoriasis subjects, the combined score of IL-17A and KLK-7 was significantly downregulated after apremilast treatment." (PMID 31953524, 2020).
psoriasis (continued). "Psoriasis-related cytokines such as IL-17A and TNF-α induced ET-1 expression in human keratinocytes." (PMID 32528072, 2020). "In active psoriasis, we observe increased expression of IL17A, IL22 and IFN-γ in the effector T CD4+ and CD8+ cells of the epidermis in the immediate vicinity of keratinocytes, whereas cutaneous T cells show less activity of these genes." (PMID 31963581, 2020). "Secukinumab, a human immunoglobulin G1 monoclonal antibody against IL-17A, is an effective and safe biologic for psoriasis, involving skin, nails, and PsA." (PMID 33281823, 2020). "Multiple animal studies have indicated that the interaction between IL-17A and keratinocyte is the key issue in the development of psoriasis." (PMID 32070069, 2020). "The mRNA expression levels of TNF-α, IL-23p19, and IL-17A, key cytokines involved in the development of psoriasis, were also increased in the IDO2 KO mice." (PMID 32752186, 2020). "S100A7 is induced by calcium, vitamin D, retinoic acid, bacterial products, TNF-α, IL-17A and IL-22, and is involved in the pathogenesis of psoriasis via its chemotactic activity for neutrophils and CD4+ T lymphocytes." (PMID 32947991, 2020). "There is evidence indicating that the main sources of IL-17A in patients with psoriasis are the neutrophils, Th17 cells, mast cells, CD8+ T cells, αβ T, γδ T cells, and innate lymphoid cells in the skin lesions." (PMID 33281823, 2020). "The combination therapy attenuates IMQ-induced psoriasis-like inflammation by downregulating the levels of IL-17A, IL-22, IL-23, and TNF-α in the serum and skin and upregulating Treg cells compared with Acar alone or low-dose CsA alone." (PMID 32316255, 2020). "The lesional skin of psoriasis harbors IL-17A-producing immune cells, and transcriptomic analysis indicates a clear predominance of IL-17A signals." (PMID 32070069, 2020). "Other antibodies, such as secukinumab, specifically targeting IL-17A were also highly effective in psoriasis patients." (PMID 33123017, 2020). "Two anti-IL17A monoclonal antibodies were approved for treatment of psoriasis, spondyloarthropathies, psoriatic arthritis, and ankylosing spondylitis, although both these antibody therapies had significant side effects." (PMID 32516406, 2020). "The K14-IL-17Aind/+ mice acquire the highest local and systemic IL-17A levels and exhibit a particularly severe psoriasis-like skin phenotype." (PMID 32070069, 2020). "With promising early clinical data in psoriasis, psoriatic arthritis, and ankylosing spondylitis, dual inhibition of IL-17A and IL-17F with bimekizumab offers a new therapeutic approach for the treatment of patients with immune-mediated inflammatory diseases." (PMID 32973785, 2020). "The KC-Tie2 mouse is a keratinocyte-specific, Tie2-overexpressing psoriasis model with cutaneous expression of IL-23 and IL-17A." (PMID 32587871, 2020). "Concerning the angiogenic role of IL-17A in psoriasis, it is important to emphasize the direct effect of this cytokine on the proliferation of IL-17R-bearing ECs, as previously reported and confirmed in this study." (PMID 32352958, 2020). "In two patients with difficult-to-treat types of psoriasis, we observed both IL-17A and IL-17F-producing KLRB1+ cells." (PMID 33329560, 2020). "Compared with healthy controls, the skin of patients with psoriasis has been shown to contain increased levels of Th17 cells with IL-17A, IL-17F, and IL-22 proteins being abundantly produced." (PMID 32392785, 2020). "In experimental asthma, lipoxins regulate NK or ILC2 activation, and in experimental psoriasis model induced by imiquimod, they reduce IL-17A and IL-22 production via HMGB1 modulation." (PMID 32161582, 2020). "Two anti-IL-17A antibodies, ixekizumab, and secukinumab, are approved for the treatment of patients with psoriasis, psoriatic arthritis, and ankylosing spondylitis." (PMID 32973785, 2020).
psoriasis (continued). "Innate immune cells like type 3 innate lymphoid cells, γδT cells, or invariant natural killer T cells also produce IL-17A and are involved in the development of psoriasis." (PMID 32751360, 2020). "Although the pathogenic significance of IL-17A is not fully understood in AD, IL-17A plays a critical role in the pathogenesis of psoriasis, as indicated by the excellent efficacy of anti-IL-17A biologics for psoriasis." (PMID 32751111, 2020). "IL-17a is a prominent cytokine in psoriasis pathogenesis, and its inhibition with neutralizing antibody recently showed successful outcome in treating patients." (PMID 32139717, 2020). "We show here that peptide self-assemblies displaying B-cell epitopes from IL-17A and exogenous T-cell epitopes can raise IL-17A-specific antibodies and diminish symptoms of imiquimod-induced psoriasis in mice." (PMID 32973764, 2020). "Though Th17 cells and IL-17A+γδ+T cells are two major IL-17A producers in psoriasis, their differentiation mechanism is different." (PMID 32454795, 2020). "In particular, IL-17A antagonists have been used for the treatment of rheumatoid arthritis and psoriasis." (PMID 33162887, 2020). "Notable pathways included, “Role of IL-17A in Psoriasis”, “T Cell Receptor Signalling”, “CD28 Signalling in T helper Cells” and “IL-8 Signalling”." (PMID 32886659, 2020). "Subsequently, a number of late phase clinical trials tested the effects of blocking IL-17A and IL-23 on aortic vascular inflammation in patients with psoriasis." (PMID 33117403, 2020). "The infiltration of Th17 cells under the skin and excessive production of IL17A lead to the pathophysiology of psoriasis and PsA." (PMID 32983137, 2020). "Recently, vitamin D was reported to suppress the expression of hBD2, hBD3, IL-17A/F and IL-8 in psoriasis plaques and induce CD4+CD25+ regulatory T cells." (PMID 32947991, 2020). "In a model of moderate to severe form of psoriasis with a late onset, anti-IL-17A treatment have beneficial effects on both vascular inflammation and dysfunction." (PMID 32352958, 2020). "IL-36 signaling in keratinocytes is crucial for Aldara-induced psoriasis-like dermatitis by controlling IL-23/IL-17A/IL-22 production and neutrophil recruitment at the third day of treatment." (PMID 32345660, 2020). "The recent therapeutic success of anti-tumour necrosis factor (TNF)-α and anti-IL-17 antibodies has emphasized the critical roles of TNF-α and IL-17A in psoriasis development." (PMID 32194991, 2020). "IL-17A is critically involved in the pathogenesis of psoriasis and several drugs targeting the IL-17A pathway have been developed and are currently used in the clinical practice." (PMID 32352958, 2020). "IL-36α, IL-36β and IL-36γ are also inflammatory cytokines up-regulated in psoriasis and induced by various stimuli, including IL-17A." (PMID 32352958, 2020). "These mice develop psoriasiform skin inflammation that is partially dependent on the cytokines IL-17A and IL-23, which play important roles in human psoriasis." (PMID 32597759, 2020). "IL-19 has been proposed as a member of the inflammatory IL-23A/IL-17A cascade in psoriasis; its upregulation in keratinocytes is driven by IL-17A, and it acts in an autocrine fashion on keratinocytes to amplify the effects of IL-17A." (PMID 31964744, 2020). "Recent clinical studies have shown that dual IL‐17A and IL‐17F blockade by bimekizumab results in rapid and profound efficacy in the treatment of PsA 20 and psoriasis." (PMID 31850514, 2020). "A similar finding has been recently described in a psoriasis murine model where the administration of anti- IL-17A or IL-23p19 induced a significant increase in the number or Foxp3+ IL-10+ Treg cells." (PMID 32630692, 2020). "In the case of IL-17A, such a reduction has also been shown during treatment of other autoimmune diseases, such as psoriasis, rheumatoid arthritis and multiple sclerosis." (PMID 32106855, 2020).
psoriasis (continued). "Antibodies against IL-17A or IL-17RA are proven to be effective in the treatment of psoriasis in humans." (PMID 31936879, 2020). "As the clinical response to anti-IL-23/IL-17A biologics seems better than that to anti-TNF-α biologics in psoriasis, the IL-23/IL-17A axis likely plays a more crucial role than the TNF-α axis in the development of psoriasis." (PMID 32070069, 2020). "In psoriasis subjects, we identified IL-17A and KLK-7 as robust biomarkers to PASI total severity scores, which were significantly downregulated by apremilast, making the two biomarkers uniquely positioned to link disease- and apremilast- centric biology." (PMID 31953524, 2020). "Serum IL-17A, IL-22, and IL-6 concentrations were significantly higher in psoriasis patients compared with the control group." (PMID 33171607, 2020). "CD3+ DN T cells are typically found in low numbers in peripheral tissues but contributing IL-17A against viral and bacterial pathogens and in autoimmune diseases such as psoriasis and Sjögren’s syndrome." (PMID 32391008, 2020). "The dysregulated expression of FLG, FLG2, LOR, and IVL is known to be normalized by specific biologic treatments, for example, blockade of interleukin-4 (IL-4) and IL-13 in AD or blockade of IL-17A in psoriasis." (PMID 32751111, 2020). "The gene expression of TNF, IL23, and IL17A is upregulated in the skin lesions of psoriasis patients." (PMID 31936670, 2020). "Secukinumab, a monoclonal antibody against IL-17A, was originally registered for treatment of psoriasis, ankylosing spondylitis, and psoriatic arthritis." (PMID 32968566, 2020). "To examine the regulation of ET-1 expression in the epidermis in psoriasis, we investigated the expression of ET-1 in human keratinocytes after stimulation with psoriasis-related cytokines such as IL-17A and TNF-α." (PMID 32528072, 2020). "The baseline serum levels of psoriasis-related cytokines (IL-6, IL-17A, and IL-23A) were the same between WT and PD-1−/− mice (n = 3)." (PMID 33060784, 2020). "IL-17A, which is expressed both in wounded skin and psoriasis skin, plays important roles in wound healing, tissue regeneration, and carcinogenesis." (PMID 32075269, 2020). "Wnt signaling pathway plays a vital role in chronic inflammatory diseases as psoriasis, such as Il-17A, it inhibits the wnt signal pathway and rescues the expression of wnt target gene and bone formation." (PMID 32795328, 2020). "It is worth noting that the mRNA expression of IL-17A was low or below the detection limit in both the psoriasis patient group and the control group." (PMID 32382290, 2020). "In the psoriasis context, IL-36 cytokines, together with IL-17A, impair keratinocyte differentiation by inducing a proinflammatory skin phenotype." (PMID 32352958, 2020). "A metanalysis in 2017 showed higher PASI 75, PASI 90 and PASI 100 response rates for psoriasis patients receiving IL-17A inhibitors compared with a placebo group." (PMID 32512854, 2020). "Serum BD‐2, an easily measurable protein, can possibly be used as a suitable surrogate biomarker to monitor responses to IL‐17A‐targeted therapies for psoriasis in clinical practice." (PMID 32173900, 2020). "Recently, it has been reported that anti-IL-17A antibody drugs show remarkable therapeutic effects in psoriasis patients." (PMID 32059488, 2020). "In psoriasis, neutrophils infiltrate into the epidermis and secrete IL-17A, which induces basal keratinocytes proliferation, followed by the production of IL-23 and TLR4." (PMID 33253155, 2020). "In parallel, the importance of IL-17A and keratinocyte interaction is reinforced in patients with psoriasis who are successfully treated with the anti-IL-17A biologic." (PMID 32070069, 2020). "We chose stimuli known to be relevant in the pathogenesis of psoriasis like IL-17A, IL-17F, TNFα, IL-1α, flagellin as well as murine S100A8 as endogenous Toll-like receptor (TLR)-trigger." (PMID 33643287, 2020).
psoriasis (continued). "Ingenuity pathway analyses of the microarray data highlighted ‘The role of IL-17A in Psoriasis’ as the canonical pathway most activated following treatment of VK2E6/E7 cells with E + F." (PMID 32439855, 2020). "Ixekizumab, a monoclonal antibody that selectively targets IL-17A, was shown to reduce depression in approximately 40% of psoriasis patients." (PMID 33134822, 2020). "High abundance of these S100-proteins during psoriasis can be explained especially by the effects of IL-17A, IL-17F, TNF, and IL-1α on S100A8/S100A9 expression, which are all central players in the pathogenesis of psoriasis." (PMID 33643287, 2020). "Blocking IL-17A signals was a promising strategy to treat IL-17A related autoimmune diseases like psoriasis, rheumatoid arthritis and ankylosing spondylitis." (PMID 32391010, 2020). "Accordingly, blockade of Th17-derived IL-17A and the Th17-inducing cytokine IL-23A are both highly efficacious for skin disease in most patients with psoriasis." (PMID 33117403, 2020). "Although IL-17A is known to be the more potent of the two cytokines, IL-17F is the more abundantly expressed of the two in psoriasis and spondyloarthritis." (PMID 32973785, 2020). "Differentiated KCs have been suggested to be the primary responders to IL-17A in psoriasis on the basis of previous studies by using in vitro KC systems, given larger effect sizes in differentiated compared with monolayer KCs." (PMID 33053333, 2020). "The expression of cytokeratin 16 is upregulated in the lesional epidermis of psoriasis patients and in keratinocytes incubated with IL-17A." (PMID 32070069, 2020). "Lastly, ILC3s are one of the subtypes of immune cells in the skin capable of producing IL-17A and IL-22 and are therefore of specific interest when discussing psoriasis." (PMID 32153574, 2020). "Pathogenetic hallmarks of PPPP include increased cutaneous expression of IL-17A and, in contrast to psoriasis, lower IL-23 expression." (PMID 33178709, 2020). "In patients, the severity of psoriasis correlated with high blood glucose levels, and anti-IL-17A monoclonal antibody therapy reduced HbA1c levels significantly in these patients." (PMID 32121574, 2020). "In psoriasis, even during remission, they become a source of important inflammatory cytokines IL-17A and IL-22." (PMID 31963581, 2020). "IL-17A had been previously reported as a known driver for psoriasis and its downregulation by apremilast was described as a molecular mechanism of action to explain efficacy." (PMID 31953524, 2020). "Therapeutic success by specific biologics points to the pathogenic role of the tumor necrosis factor-α (TNF-α) axis and the interleukin (IL)-23/IL-17A axis in psoriasis." (PMID 31936670, 2020). "IL-17A is known to have a crucial role in the psoriasis’ pathogenesis: its skin expression is closely related to the development of skin lesions, with an increase starting after one day of IMQ application." (PMID 32825447, 2020). "detected levels of IL‐17F and IL‐17A in the serum of PsA, AS, and psoriasis patients using a highly sensitive Singulex immunoassay." (PMID 31850514, 2020). "Treatment with mimic-340 alleviated the psoriasis severity in the same mouse model through the downregulation of cytokine IL17A." (PMID 33321931, 2020). "The success of IL-17A-based medications against other immune disorders (e.g., psoriasis and arthritis) implies that translating these in vitro findings into future therapies is feasible." (PMID 31083515, 2019). "Although TIPE2-deficient T cells produced more IL-17A, TIPE2-deficient mice produced much less IL-17A in the skin and displayed reduced severity of IMQ-induced psoriasis." (PMID 31616442, 2019). "Currently, we know that the inflammatory components of the interleukin (IL)-17A-driven skin disease play a striking role in linking severe psoriasis and cardiovascular mortality." (PMID 31480330, 2019).